CHEK1 (checkpoint kinase 1)
Diseases named in the same sentence as CHEK1 in open-access papers (continued):
Sharing a sentence is not in itself a finding about the gene and the disease.
prostate carcinoma (50 papers, 2004 to 2025). A carcinoma that arises from epithelial cells of the prostate gland. "ATR and CHEK1 expression levels are often elevated in many forms of cancer, including ovarian, breast and prostate cancer and correlate with poor outcomes for patients." (PMID 38669256, 2024). "To further demonstrate the role of CDC25C, we used pharmacological inhibitors of PLK1 and CHEK1, in our LZTS1-deficient Docetaxel resistant prostate cancer cells." (PMID 24525428, 2014). "CHEK1 contributes to CDC25C-mediated Docetaxel resistance and can also be a therapeutic target in prostate cancer." (PMID 32503434, 2020). "For example, prostate cancer Phase IB/II trials are ongoing for the CDK4/6 inhibitors ribociclib (ClinicalTrials.gov identifier: NCT02555189, NCT02494921) and palbociclib (NCT02905318, NCT02059213), and the CHEK1 inhibitor LY2606368 (NCT02203513)." (PMID 30616540, 2019).
triple-negative breast carcinoma (45 papers, 2012 to 2025). An invasive breast carcinoma which is negative for expression of estrogen receptor (ER), progesterone receptor (PR), and human epidermal growth factor receptor 2 (HER2). "Recent studies have shown that inhibition of kinases related to cell cycle check points, including checkpoint kinase 1 (CHK1), polo-like kinase 1 (PLK1), or aurora kinase A or B, exhibits synthetic lethality in combination with RB deficiency in triple-negative breast cancer (TNBC) or SCLC." (PMID 32244804, 2020). "In triple-negative breast cancer models, KLT effectively blocked cell cycle progression at the G2/M phase by downregulating CDK1, CDK2, and CHEK1, inhibiting CDC25A, CDC25B, MELK, and AURKA activity, suppressing mitosis, and inducing apoptosis." (PMID 41164166, 2025). "Our previous study found that the checkpoint kinase 1 (Chk1) inhibitor PD407824 suppresses the growth and motility of triple-negative breast cancer cell lines as well as in an allograft model." (PMID 34124754, 2021). "This study aimed to investigate the targeting of checkpoint kinase 1 (CHK1), a critical player regulating the G2/M checkpoint, as a promising strategy to potentiate PBT in human triple-negative breast cancer (TNBC) cells." (PMID 32294924, 2020).
melanoma (44 papers, 2008 to 2026). A malignant, usually aggressive tumor composed of atypical, neoplastic melanocytes. "The BRCA1 and CHEK1 variants were identified in a rare breast neuroendocrine tumor (GE05) and in a melanoma case (GE14), respectively." (PMID 38750555, 2024). "A number of genes such as Checkpoint Kinase 1 (CHEK1) showed an association of mutational patterns and occurrence of splice variants in melanoma." (PMID 34281234, 2021). "Moreover, the prognostic significance of CHEK1 has been explored in various cancers, such as melanoma, lung adenocarcinoma, hepatocellular carcinoma, and BrC." (PMID 40344565, 2025). "Whether the increased expression of BRCA1 and CHEK1 may account for the increased expression of cell cycle genes and decreased expression of apoptotic target genes in melanoma is yet to be determined." (PMID 21615965, 2011). "RSK promotes G2 DNA damage checkpoint silencing by phosphorylating checkpoint kinase 1 (Chk1) at Ser280, and inhibition of RSK can sensitize melanoma cells to DNA‐damaging chemotherapy." (PMID 41492362, 2026). "Eight inhibitors targeting Wee1, Checkpoint kinase 1/2, Aurora kinase, MEK, Polo-like kinase, PI3K and Focal adhesion kinase killed melanoma cells synergistically when combined with a BRAFi." (PMID 30728057, 2019). "Pathway analysis suggests that CDC2, CHEK1, CDC45L and MCM6 are key players in mediating the biological activity of RA in B16 melanoma cells." (PMID 18847503, 2008). "The increased abundance of Chk1 protein in melanoma cells with increased LAMP-2C expression was not due to higher CHEK1 mRNA levels, but rather an increase in Chk1 protein abundance including Chk1 molecules phosphorylated at Ser345." (PMID 30211163, 2018). "Increased cellular expression of Chk1 and IκBα was not due to higher CHEK1 and NFKBIA mRNA transcripts, again consistent with CMA disruption in melanoma cells with high LAMP-2C expression." (PMID 30211163, 2018).
glioma (43 papers, 2013 to 2026). A benign or malignant brain and spinal cord tumor that arises from glial cells (astrocytes, oligodendrocytes, ependymal cells). "ATRX mutation in glioma disturbed the cell-cycle phase transition, downregulated the expression of Checkpoint Kinase 1 (CHEK1) and even inhibited radio-sensitization." (PMID 37570630, 2023). "The radiosensitivity of glioma stem cells is promoted when the DNA damage repair protein, checkpoint kinase 1 (CHK1), is degraded following HDAC6 inhibition." (PMID 39941046, 2025). "Our study describes the potential therapeutic value of combining a Checkpoint kinase 1/2 inhibitor with immune checkpoint blockade in murine glioma models." (PMID 36949040, 2023). "In our study, pharmacological inhibition of Chek1/2 by Prexasertib and AZD7762, two different inhibitors proven safe in clinical trials, rendered gliomas susceptible to PD-1 blockade in glioma models." (PMID 36949040, 2023). "A new regulatory axis between CCAT2/miR-424 and the protein checkpoint kinase 1 (CHK1) gene was described in glioma, with roles in the tumor chemoresistance." (PMID 34830370, 2021). "A synthetic lethality screen of 714 kinases in pediatric gliomas identified checkpoint kinase 1 (CHK1) and aurora kinase A (AURKA), both MYC stabilizing proteins, and usage of a small molecule inhibitor of AURKA (VX-689) exhibited potent cell killing in vitro." (PMID 30340362, 2018). "The results showed that CCND1, CDC42, RAF1, and CHEK1 were highly expressed in gliomas." (PMID 33676540, 2021). "Checkpoint kinase 1 (Chk1) is another promising target for glioma therapy." (PMID 34440090, 2021). "Independently, miR‐195‐5p has been described as a regulator of the CHEK1 gene in non‐small cell lung and gastric carcinoma, and CCNE1 in glioma." (PMID 40548926, 2025). "The study suggests that LINC00466 may exert anti-oncogenic effects in glioma through its interaction with the miR-508/CHEK1 axis, presenting LINC00466 as a potential prognostic and therapeutic target for glioma." (PMID 38893192, 2024).
hepatocellular carcinoma (43 papers, 2009 to 2026). A malignant tumor that arises from hepatocytes. "All these findings demonstrate that CELSR3, GPSM2, and CHEK1 were upregulated in hepatocellular carcinoma and linked to prognosis of patients with hepatocellular carcinoma." (PMID 32257949, 2020). "Additional research using bioinformatics analysis and experimental validation has revealed that the CHEK1 gene is highly expressed in hepatocellular carcinoma and indicates poor prognosis." (PMID 41564103, 2026). "In hepatocellular carcinoma, CHEK1 activates CDC25C through phosphorylation, relieving CDK1 inhibition and promoting the G2/M phase transition, thus accelerating proliferation." (PMID 41564103, 2026). "In hepatocellular carcinoma, inhibition of checkpoint kinase 1 (CHK1) increases IRF1 expression to induce apoptosis and trigger antitumor immunity through major histocompatibility complex (MHC) class I-associated chain A (MICA)." (PMID 38789431, 2024). "The aim of this study is to elucidate the functional mechanism of the miRNA-424-5p/CHEK1 pathway in hepatocellular carcinoma (HCC), thereby offering novel insights for the development of targeted therapeutic strategies for HCC." (PMID 39309825, 2024). "Four cell cycle-related genes (CDK4, CHEK1, CCNB1, and CDKN2A) were used to establish a risk score to predict the overall survival (OS) of patients with hepatocellular carcinoma (LIHC) in TCGA training set using LASSO Cox regression analysis." (PMID 36403263, 2022). "Next, Oncomine database was further introduced to analyze CELSR3, GPSM2, and CHEK1 expression in hepatocellular carcinoma." (PMID 32257949, 2020). "A previous study identified CHEK1 as a target of miR-497 in hepatocellular carcinoma, and CHEK1 is the target gene of lncRNA CASC9/miR-497 axis in BC." (PMID 32766141, 2020). "CELSR3, GPSM2, and CHEK1 expression were markedly higher in hepatocellular carcinoma than that in normal controls." (PMID 32257949, 2020). "Theoretically, miRNAs that potentially bind to oncogenic CELSR3, GPSM2, and CHEK1 should be downregulated in hepatocellular carcinoma and display favorable prognostic roles." (PMID 32257949, 2020). "All these findings indicate that high expression of CELSR3, GPSM2, or CHEK1 links to unfavorable prognosis of patients with hepatocellular carcinoma." (PMID 32257949, 2020). "The results suggested that high expression of CELSR3, GPSM2, or CHEK1 indicated poor prognosis in patients with hepatocellular carcinoma." (PMID 32257949, 2020). "Later, Fang and Beland (2009) using a hepatoma cell line (HepG2) indicated that AZT caused a decrease in checkpoint kinase 1 (Chk1) and kinase 2 (Chk2) and an increase in phosphorylated Chk1 (Ser345) and Chk2 (Thr68)." (PMID 22973556, 2012). "Previous reports suggested that checkpoint kinase 1 (CHK1) is activated in response to genotoxic damage, and phosphorylation of Syk on S295 by CHK1 promotes tumorigenesis in hepatocellular carcinoma via Syk degradation, but these signaling pathways were inconsistent with our results." (PMID 37330581, 2023). "Therefore, CELSR3, GPSM2 and CHEK1 were considered as three novel potential prognostic biomarkers for hepatocellular carcinoma." (PMID 32257949, 2020). "Among them, CDK1, CHEK1, TYMS, KIF11, MMP12, TK1 and CA12 were differentially highly expressed in hepatocellular carcinoma tissues." (PMID 38842135, 2024). "The TCGA hepatocellular carcinoma cohort was used for internal and external validation and further screening to derive the three core genetic markers, including NR1I2, CDK1, and CHEK1." (PMID 38842135, 2024). "CHEK1-hsa-mir-195-5p/hsa-mir-497-5p and GPSM2-hsa-mir-122-5p axes were defined as two key pathways in carcinogenesis of hepatocellular carcinoma by combination of in silico analysis and experimental validation." (PMID 32257949, 2020).
hepatocellular carcinoma (continued). "Using a model of chemically induced hepatocellular carcinoma in mouse liver, we comparatively analyzed the dynamics of transcript levels for several genes (BRCA1, BRCA2, CHEK1, CHEK2, ATM, CDK12) in paired samples of normal and tumor tissue over a 24-h PMI using RT-qPCR." (PMID 42073491, 2026). "CHEK1, CDC25A, and CCNE1, together with CCND1, CCND3, CDK4, CDK6, BTRC, E2F3, and FOXK1, were previously identified as the targets of miR‐497∼195 cluster in hepatocellular carcinoma." (PMID 40548926, 2025). "Among the 14 intersecting genes, lasso regression was used to screen for genes with higher prognostic correlation with hepatocellular carcinoma, and a crossover test was performed to screen for three genes with higher prognostic correlation with patients—NR1I2, CDK1, and CHEK1." (PMID 38842135, 2024). "Some groups investigated the upstream of SYK in hepatocellular carcinoma, and the results indicated that SYK can be regulated by checkpoint kinase 1 (CHK1) effectively, and the phosphorylation of SYK induced by CHK1 enhances the subsequent proteasomal degradation of SYK in hepatocellular carcinoma." (PMID 36568669, 2022). "Based on these findings, a potential miR-497-mRNA or miR-1246-mRNA regulatory network can be established, namely, miR-497-ARL2/UBE2Q1/PHF19/APLN/CHEK1/CASK/SUCO/CCNE1/KIF23, or miR-1246-AUTS2/SLAIN1, which contributes to the occurrence and development of hepatocellular carcinoma." (PMID 34163524, 2021). "Our current findings together with these reports suggest that CHEK1-hsa-mir-195-5p, CHEK1-hsa-mir-497-5p, and GPSM2-hsa-mir-122-5p may be key pathways in pathogenesis of hepatocellular carcinoma." (PMID 32257949, 2020). "In the study, we found that therapy target genes of Jianpi Jiedu decoction were mainly involved in metabolism and apoptosis in hepatocellular carcinoma, and there was a close relationship between the prognosis of hepatocellular carcinoma and the genes of CCNB1, NQO1, NUF2, and CHEK1." (PMID 33424998, 2020). "The rest three genes (CELSR3, GPSM2, and CHEK1) have not been studied for their prognostic values in hepatocellular carcinoma so far." (PMID 32257949, 2020). "In hepatocellular carcinoma (HCC), downregulation of CHEK1 by silencing LINC01224 or elevating miR-330-5p could inhibit stemness, by reducing the expression of CSC biomarkers (OCT4, CD133 and SOX2)." (PMID 32121037, 2020). "All these results together indicate that CHEK1-hsa-mir-195-5p/hsa-mir-497-5p and GPSM2-hsa-mir-122-5p may be key pathways in mediating progression of hepatocellular carcinoma and that link to patients' prognosis." (PMID 32257949, 2020). "To determine the clinical value of targeting CHK1 and BRD4 in MYC‐driven HCC, we assessed the role of CHEK1 and BRD4 expression in the pathogenesis of HCC in patients from the Genomic Data Commons (GDC) The Cancer Genome Atlas Liver Hepatocellular Carcinoma (TCGA‐LIHC) data set." (PMID 36684069, 2023).
non-small cell lung carcinoma (42 papers, 2010 to 2025). A group of at least three distinct histological types of lung cancer, including non-small cell squamous cell carcinoma, adenocarcinoma, and large cell carcinoma. "It has been demonstrated that upregulation of CHEK1 can ameliorate the overall survival of non-small-cell lung cancer patients and miR-195 downregulates the expression level of CHEK1, which inhibits cell migration, growth, or invasion." (PMID 34545328, 2021).
leukemia (39 papers, 2010 to 2025). A malignant (clonal) hematologic disorder, involving hematopoietic stem cells and characterized by the presence of primitive or atypical myeloid or lymphoid cells in the bone marrow and the blood. "Excluding the SYNE1, NOTCH4, and CHEK1 genes, all others are well known leukemia/lymphoma cancer genes with a tier 1 category in the Cancer Gene Census database." (PMID 34573308, 2021). "Our results correlate with previous studies, which have shown the use of CHEK1 inhibitors in leukemias." (PMID 33921415, 2021). "While DDR protein activation was not discernable from the mRNA GEP studies, several other reports note connections between leukemia and abnormalities in activated DDR proteins such as CHEK2.pT68 and CHEK1.pS345." (PMID 36982970, 2023). "Given prior reports of synergy between CHEK1 and WEE1 inhibitors in lymphoma, leukemia, and solid tumor cell lines, we suspected that simultaneous inhibition of CHEK1 and WEE1 might further magnify the synthetic lethal effect with RAD17 knockdown." (PMID 26437225, 2015). "Also, in our leukemia model, ERG under-expressed genes included ATM, CHEK1 and ATR, which are key genes in the initiation of homology-dependent DNA repair." (PMID 24504051, 2014).
glioblastoma (38 papers, 2010 to 2026). The most malignant astrocytic tumor (WHO grade IV). "RRM2 is a promising therapeutic target for glioblastoma, and the use of triapine can effectively target RRM2, making glioblastoma cells more sensitive to radiation and inducing synthetic lethality when combined with checkpoint kinase 1 inhibition." (PMID 40625451, 2024). "For instance, ATRX binds to regulatory elements of cell cycle genes including CHEK1, as previously reported in a glioblastoma model." (PMID 38978571, 2024). "This study discusses our assessment of CDK1/PBK/CHEK1′s potential as theragnostic and prognostic markers in glioblastoma." (PMID 38003585, 2023). "The molecular docking results confirmed the potential of Dapagliflozin in inducing apoptosis by arresting the cell cycle by targeting CDK1, PBK, and CHEK1 in glioblastoma." (PMID 38003585, 2023). "Therefore, we tested a new strategy to overcome the high radio- and chemotherapy resistance of glioblastoma cells using the checkpoint kinase 1 (Chk1) inhibitor SAR-020106 (SAR) and the epigenetic modulator and cytotoxic agent decitabine (5-aza-2’-deoxycytidine, 5-aza-dC)." (PMID 31639020, 2019). "For example, in glioblastoma (GBM), inhibition of checkpoint kinase 1 (Chk1) and checkpoint kinase 2 (Chk2) activity decreased its resistance to radiotherapy." (PMID 35205721, 2022). "HDAC6 also promoted the proliferation of glioblastoma by increasing the levels of DNA damage response genes such as DNA repair protein 51 (RAD51) and checkpoint kinase 1 (CHEK1)." (PMID 36076996, 2022). "However, the simultaneous inhibition of the chemo radio-resistant CDK1/PBK/CHEK1 oncogenic signature in glioblastoma has never been explored despite the existing cell cycle crosstalk amongst these genes." (PMID 38003585, 2023).
lymphoma (37 papers, 2012 to 2024). A malignant (clonal) proliferation of B- lymphocytes or T- lymphocytes which involves the lymph nodes, bone marrow and/or extranodal sites. "Despite the acute therapeutic effects in lymphoma by deleting the wild-type alleles of Chek1, lymphomas eventually relapsed in the mice." (PMID 32571801, 2020). "Mice transplanted with λ-Myc;CreER;Chek1Flox/wt;Cdkn2a+/− lymphoma cells did not respond at all to tamoxifen, again demonstrating that one allele of Chek1 is sufficient for lymphoma cells to survive." (PMID 32571801, 2020). "Currently, multiple CHEK1 inhibitors have been commercially developed and showed promising results in pre-clinical studies for cancer types like lymphoma and neuroblastoma." (PMID 35903365, 2022). "We also investigate the role of Chek1 in lymphoma, in erythropoiesis and in T-cell–mediated tumor cell killing, using inhibitors and/or mice expressing a kinase-dead Chek1 allele." (PMID 32571801, 2020). "Eμ-Myc/cRel−/− lymphomas have downregulated the expression of USP1 and checkpoint kinase 1 (CHK1) protein that results in resistance to treatment by specific CHK1i." (PMID 39664521, 2024).